IL1B (interleukin 1 beta)
Diseases named in the same sentence as IL1B in open-access papers (continued):
Sharing a sentence is not in itself a finding about the gene and the disease.
tumor (continued). "Pre‐treatment with the IL‐R antagonist, anakinra or siRNA to IL‐1R1 significantly reduced chemokine secretion from NTF stimulated with conditioned medium from HPV‐negative tumour cells or recombinant IL‐1β (p < 0.05)." (PMID 30191960, 2019). "In this scenario, local bacteria induce MyD88-dependent IL-1β and IL-23 secretion from myeloid cells, thus enhancing the proliferation and activation of γδ T cells, which induce IL-17-mediated inflammation and tumour cell proliferation." (PMID 31438559, 2019). "Noticeably, tumor-specific Th9IL-4+IL-1β cells are cytolytic effectors and endowed with robust antitumor function." (PMID 30914642, 2019). "In summary, our study reveals tumour-promoting functions of CAFs in sensing tumour-induced tissue damage, leading to activation of the NLRP3 inflammasome pathway and secretion of IL-1β, which promotes tumour progression and lung metastasis." (PMID 31558756, 2019). "We therefore examined if the disruption of IL1β production and signaling in the tumor microenvironment would augment the cytostatic effect of Tam on the ER+BCCs." (PMID 31419632, 2019). "Previous studies showed that IL-1β enhances tumorigenesis and the invasiveness of malignant tumors, including HCC, because IL-1β is a key cytokine for maintaining tumor microenvironment." (PMID 30794626, 2019). "Analysis of the results revealed that genetic depletion of Il1b in fibroblasts in the primary tumour led to a significant decrease in the expression of E-Selectin, P-Selectin, ICAM-1 and VCAM-1 and in ECs sorted from primary tumours." (PMID 31558756, 2019). "Together, these data suggest that IL-1β can be safely administered to improve the efficacy of ACT by enhancing the tumor infiltration and functionality of antitumor T cells." (PMID 31405895, 2019). "These suggest that the activation of NLRP3 inflammasome in macrophages by ATP of which level is high in tumor microenvironment, results in the increased production of IL-1β and the promotion of tumor cell metastasis." (PMID 31439870, 2019). "There are several types of DC-vaccines, being the most frequently used the reinfusion of ex vivo derived DC pulsed with tumor-associated antigens (TAAs) or tumor cell lysates and stimulated with TNF-α, IL-1β, IL-6, and prostaglandin E2 (PGE2)." (PMID 31998254, 2019). "IL-1β was shown to originate from tumor-infiltrating CD11c+ myeloid cells with production triggered by cancer cell-derived TGFβ." (PMID 31231372, 2019). "In this prior study, we showed that neutrophil-derived IL-1β production mediates a portion of the increased tumor formation identified in IKKβΔMye mice." (PMID 31903163, 2019). "All mice were injected with tumour cells, and mice were treated with an anti-mouse IL1β antibody, the anti-human Frizzled receptor antibody Vantictumab, or with vehicle control." (PMID 31676788, 2019). "Increased expression of CTH in bone‐metastatic PC cells induced a change in H2S level, resulting in the activation of IL‐1β/NF‐κB‐mediated signaling to promote cell invasion, angiogenesis, lymphangiogenesis, tumor growth, and metastasis." (PMID 31468690, 2019). "For example, tumor-derived cytokines, including IL-6 and IL-1β, as well as cytokines released from activated T cells, such as IL-4 and IL-10, develop common myeloid progenitor cells into MDSCs." (PMID 31048856, 2019). "Direct comparisons of these two phenotypically distinct Th9 cells suggests that Th9IL-4+IL-1β cells display higher tumor-specific cytotoxicity in vitro and improved tumor clearance in vivo compared to classic Th9IL-4+TGF-β cells." (PMID 30914642, 2019). "Secretion of CRCSC chemokines then helps in the recruitment of exosome-trained neutrophils to primary tumors (proximal effect, the second tumor-host interaction) to accelerate tumorigenesis induced by IL-1β." (PMID 30683126, 2019).
tumor (continued). "Among them, the nerve growth factor (NGF) and the brain-derived neurotrophic factor (BDNF) cause axonal chemoattraction, and IL-6, IL-8, IL1b, and CCL5 foster tumor-associated hyperalgesia." (PMID 30825056, 2019). "IL-1β activates vascular endothelial growth factor, which promotes blood vessel growth and provides nutrients for tumor growth." (PMID 31832112, 2019). "In fact, protein analysis of the tumor revealed increased IL1β and IL6 content only 12 and 24 h after tumor induction." (PMID 31712726, 2019). "Our data identified that in response to tumor cell-derived IL-1β and TNF-α, astrocytes not only continued to express TGF-β2, but the expression increased significantly." (PMID 31602400, 2019). "We found that the administration of IL-1β increased the population size and functionality of adoptively transferred T cells within the tumor." (PMID 31405895, 2019). "Herein, we found that infiltrating tumor cells produced significant levels of IL-1β in response to intravenous injection of engineered bacteria, resulting in inhibition of tumor growth." (PMID 31754923, 2019). "Specifically in CC-group, a positive correlation was found between ANGPTL-4 levels and those of IL-1β, TNF-α, and NFκB in tumor, along with an association between ANGPTL-4 levels with IL-1β and MCP-1 levels in tumor; and ANGPTL-4 and IL-1β levels in MES." (PMID 31741709, 2019). "Next, to analyze the immunological changes resulting from administration of the anti-cancer drug in the C57BL/6N mouse stocks, we evaluated the expressions of IL-1β, IL-6 and IL-10 gene isolated from tumor tissue by real-time PCR." (PMID 32257905, 2019). "Nevertheless, in the current work, elevated brain Il1α and Il1β gene expression negatively predicted open field locomotion in all mice exposed to a tumor (combined tumor-bearing and -resected groups)." (PMID 31019214, 2019). "The tumor microenvironment provides favorable conditions for the enrichment of IL‐17‐producing γδ T cells, notably through enhanced levels of the cytokines IL‐1β, IL‐6, IL‐23 and IL‐7, which favor CD27− γδ T‐cell survival and promote IL‐17 expression." (PMID 31624593, 2019). "We found that tumours co-injected with CAFs in which Nlrp3 or Il1b were depleted had significantly downregulated expression of pro-inflammatory genes related to immune cell recruitment." (PMID 31558756, 2019). "For example, astragalus saponins, astragalus and angelica polysaccharides, ferulic acid, and Z-ligustilide are known to suppress expression of some tumor-promoting cytokines, such as IL-1β, IL-6, and TNF-α." (PMID 31781219, 2019). "Circulating levels of IL-1β and CXCL1 were higher in the light phase for tumor-free control mice (IL-1β: t8 = 2.3, p < 0.05; CXCL1: t8 = 10.9, p < 0.0001), but these time-of-day differences were lost in both the tumor-bearing and -resected mice." (PMID 31019214, 2019). "Remarkably, anakinra did not affect the growth of 67NR tumors, possibly reflecting the minor participation of the IL-1β/G-CSF axis in 67NR tumor progression." (PMID 31552036, 2019). "The ability of CXC ligands and IL1b to enhance tumor effects was also observed in a soft-agar assay utilizing human primary esophageal epithelial cells." (PMID 31041783, 2019). "We examined the immune cells mediating S.t-ΔpGlux/pT-ClyA-induced tumor suppression and examined the major cell types producing IL-1β." (PMID 31754923, 2019). "Pro-inflammatory cytokines such as tumor necrosis factor (TNF)-α, interleukin (IL)-1β, and IL-6 are reported to participate in chronic inflammation of tumor microenvironment, thereby creating a favorable environment for tumor progression and metastasis." (PMID 31252615, 2019). "Previous therapeutic interventions against inflammatory cytokines such as IL-6 and IL-1β have failed in clinical trials despite their well-known role in tumor and metastasis promotion." (PMID 31007849, 2019). "Other studies suggested that IL-1β affects the mesenchymal transition and invasive behaviour of tumour cells." (PMID 31558756, 2019).
tumor (continued). "Multiple strands of both in vitro and in vivo evidence point toward a tumor-promoting function for IL-1β." (PMID 31231372, 2019). "The in vivo study also reproduced our findings in vitro, that is, luteolin suppressed the expressions of AIM2, pro-caspase-1, caspase-1 p10, pro-IL-1β, and IL-1β in tumor samples from nude mice." (PMID 30833546, 2019). "Contact between tumor and osteoblasts or bone marrow cells increased IL-1β secretion from all three cell types." (PMID 31847214, 2019). "As a major finding of our study, we found that IL-1β availability in the tumor is significantly sustained by tumor cell-released ASC that acts as alarmin to induce and/or amplify inflammatory responses through macrophage activation." (PMID 30760333, 2019). "On the other hand, systemic inflammation, which assists tumor grow, is related to the activation of IL-6 and IL-1β pathways which are responsible for induction of SERPINA1 expression." (PMID 31487965, 2019). "In this study, we demonstrated CRCSCs exosome-mediated IL-1β expression in neutrophils prolonged neutrophil survival, which establishes the host-tumor crosstalk for facilitating tumorigenesis through extending the survival pro-tumoral neutrophils." (PMID 30683126, 2019). "Consistent with previous studies, we found that tumor burden resulted in elevated hepatic Il1b, Ifna, Lcn2, Apcs, Crp, and Orm1." (PMID 31615993, 2019). "In the tumor mass, it is possible to detect an increase in the expression of IL1β, TNFα, and IL10 24 h after its inoculation, whereas IL6 expression increased earlier, just 12 h after cells injection." (PMID 31712726, 2019). "The 48 h coculture initiates a pro-tumor phenotype skewing of MΦ, indicated by downregulation of IL1B, IL12, CCL18, CD80, as well as CD163, and upregulation of CLEC7A (dectin-1), CD86, CD206, and HLA-DR." (PMID 30850595, 2019). "NLRP3 is constitutively activated and leads to sustained local and systemic inflammation mediated by IL-1β in the tumor." (PMID 31106156, 2019). "Subsequently, IL-1β and IL-18 trigger the activation of the adaptive immune response to viruses and tumor cells." (PMID 31554368, 2019). "At 24 h post-LPS, Il-1β remained significantly decreased in the hypothalamus in tumor-bearing mice relative to tumor-free controls (t30 = 2.7, p < 0.05), whereas tumor-resected responses remained intermediate." (PMID 30679700, 2019). "The recruited neutrophils then activate pancreatic stellate cells via IL-1β secretion to accelerate fibrosis, which promotes tumor growth and reduces sensitivity to chemotherapy." (PMID 31474975, 2019). "These suggest that ATP accumulated in tumor microenvironment would activate NLRP3 inflammasome resulting in the increased secretion of IL-1β from immune cells." (PMID 31439870, 2019). "Within the tumor microenvironment, IL-1β acts as a pleiotropic cytokine, increasing tumor growth and invasiveness via induction of MMPs, VEGF, IL-8, IL-6, TNFα, and TGFβ." (PMID 31174326, 2019). "This suggests that the IL-1β anti-tumor activity is concentration-dependent, and increasing IL-1β concentration will increase its anti-tumor effects." (PMID 31754923, 2019). "The regulatory effect of SI-CLP is not clear yet since the cytokines induced by SI-CLP can either promote (IL-1β, IL-6, IL-13) or suppress (IL-12) tumor progression." (PMID 32038607, 2019). "Gene expression analyses performed on CD11b+ tumor infiltrating immune cells isolated from EONY#17 tumors showed enhanced expression of the M1-like markers IL1β, Cxcl9, IL6 and Nos2." (PMID 31519152, 2019). "To fill the gap, herein, we examined clinical samples, including tumor and matched non-tumor biopsies and sera, collected from pretreated patients with ccRCC and investigated the role of IL-1β and complex molecule contexture elicited by IL-1β in ccRCC." (PMID 31816951, 2019).
tumor (continued). "Increased tumor incidences in Brg1IEC-AKO mice were associated with the persistent inflammation, as reflected by increased IL-6, IL-1β, TNFα and CCL2 productions in the 5 months of AOM-treated Brg1IEC-AKO mice." (PMID 31601814, 2019). "Its increased expression on tumor cells leads to tumor progression (proliferation) and metastasis, and its expression is dependent on TNFα, IL-1β, IFNγ via toll-like receptors (TLRs)." (PMID 31374832, 2019). "Mechanistically, tumor exosomal tri-phosphate RNAs induced the expression of interleukin-1β (IL-1β) through a pattern recognition-NF-κB signaling axis to sustain neutrophil survival." (PMID 30683126, 2019). "Within the tumor microenvironment, several factors lead to the production of IL-6 and IL-8, including IL-1β and TNFα." (PMID 31781510, 2019). "Joined with the pro-angiogenic and pro-inflammatory activities of IL-1β, the two cytokines were identified as pro-metastatic factors in many tumor types." (PMID 31031757, 2019). "The enhanced tumor burden was associated with reduced levels of both IL-1β and IL-18 which resulted in reduced STAT1 signaling and sub-optimal anti-tumor type I immunity." (PMID 31231388, 2019). "We evaluated correlation between GSTO1 expression and IL-1β/pro-IL-1β ratio in tumor ccRCC tissue samples and observed weak positive correlation (r = 0.260, p = 0.350)." (PMID 31861116, 2019). "The tumor-stroma-inflammation network identified in our study suggests that inhibiting the activities of TNBC-typical pro-inflammatory cytokines, such as TNFα and IL-1β would halt tumor-stroma interactions that stand in the basis of TNBC progression." (PMID 31031757, 2019). "This study demonstrated that IL-1β plays an important role in the anti-tumor process, and IL-1β source cells were primarily monocytes, macrophages, dendritic cells and neutrophils." (PMID 31754923, 2019). "In the frontal cortex, tumor resection tended to reduce Il-1β at 4 h post-LPS relative to controls, similar to mice that retained their tumors (p = 0.07)." (PMID 30679700, 2019). "Tnf-α, Il-1β, and Il-6 mRNA decreased in multiple brain regions of LPS-treated tumor-bearing mice relative to LPS-treated controls; tumor resection attenuated these effects in some cases (but not Tnf-α)." (PMID 30679700, 2019). "IL-1β is thought to play an important role in cancer invasiveness, progression, and metastases via inflammation in the tumor microenvironment." (PMID 31182982, 2019). "Tumor expression of IL1β and TNFα augmented within 24 h and IL6 within 12 h after the LPS treatment." (PMID 31712726, 2019). "As observed for G-CSF, our data showed that the IL-1β expression levels, either in cultured 4T1 cells or in the tumor mass, were substantially higher compared to those in 67NR cells in vitro or in vivo, respectively." (PMID 31552036, 2019). "Functionally, we show that CAF-derived IL-1β facilitated tumour progression and metastasis by upregulating the expression of adhesion molecules in endothelial cells (ECs), and promoting the recruitment of CD11b+Gr1+ myeloid-derived suppressor cells (MDSCs)." (PMID 31558756, 2019). "Western blot, immunofluorescence and flow cytometry analysis were used to investigate IL-1β-derived cells and IL-1β expression on tumor cells and immune cells to analyze the regulatory mechanism." (PMID 31754923, 2019). "It has been reported that tumor-derived IL-1β induces MDSCs accumulation and suppressive activity via NF-κB pathway, suggesting a relationship between inflammation, cancer, and immune suppression." (PMID 30998767, 2019). "IL-1B generated in the course of chronic inflammation supports tumour growth and metastasis predominantly by tumour-infiltrating macrophages." (PMID 31877723, 2019). "IL-1β leads to canonical NF-κB activation, which then targets and up-regulates the tumor-promoting miR-425, which targets the tumor suppressor gene PTEN." (PMID 31557902, 2019).
tumor (continued). "As predicted by our model, PDGF-BB and IL1β can only be detected in the tumor tissue, indicating that the cross talk between the TAFs and the ER+BCCs and not the normal breast epithelial cells results in PDGF-BB and IL1β production." (PMID 31419632, 2019). "In NLRP3−/− and IL-1β−/− mice models, treatment with 5-FU shows a long term tumor growth regression." (PMID 31217433, 2019). "IL-1β plays an important role in the interaction between tumor cells and their bone marrow microenvironment." (PMID 31727865, 2019). "The results would provide a novel anti-cancer strategy using NLRP3 inflammasome inhibitors, such as celastrol to modulate the myeloid cells in tumor microenvironment and tumor metastatic potential by reducing the IL-1β level at tumor sites." (PMID 31439870, 2019). "Collectively, these data suggest that tumor cells secrete/release alarmins which predominantly induce IL-1β secretion by macrophages." (PMID 30760333, 2019). "In a subcutaneous injection model used to study the tumor microenvironment, decreased intratumoral levels of IL-1β were observed by confocal microscopy in tumor-bearing mice injected with 2-DG." (PMID 30586442, 2018). "Our present findings expand the paradigm of how mutant KRAS impacts tumor–host interactions: it renders tumor cells capable of sensing inflammatory IL-1β signals originating from the CCL2-recruited monocytes." (PMID 29445180, 2018). "MCC950 inhibited NLRP3 activation and caspase-1 dependent IL-1β processing, and hence improved anti-tumor immune response in head and neck squamous cell carcinoma." (PMID 30631327, 2018). "CCL2 can be produced by bone marrow-derived stromal cells or tumor cells, while tumor cells produce IL-1β." (PMID 29686671, 2018). "Ibuprofen treatment reduces fatigue and depressive-like behaviors in tumor-bearing mice, while reducing IL-1β and IL-6 mRNA expression in the hippocampus, compared to healthy control mice." (PMID 29930550, 2018). "RT-qPCR of IRF6 and IL-1β transcripts revealed that both genes were reduced in tumor tissues compared to normal biopsies." (PMID 30089163, 2018). "A combination of these drugs with IL-1Ra or an IL-1β blocking antibody reduced side effects and smaller tumor growth." (PMID 30042333, 2018). "The secretion of ATP leads to the activation of P2RX7 receptor on DCs, resulting in the promotion of chemotaxis, tumour infiltration by inflammatory cells, and inflammasome-dependent release of the pro-inflammatory cytokines IL-1β and IL-18." (PMID 30261606, 2018). "DCs are ex vivo loaded with tumor-specific antigens and are matured under the influence of danger signals such as tumor necrosis factor-α, IL-1β and IL-6 or TLR ligands." (PMID 30235890, 2018). "We have previously shown that the MAPK activated protein kinase 2 (MK2) pathway is responsible for the majority of IL-1β, IL-6, and TNF-α production in both a colitis-associated cancer and a tumor transfer model of CRC." (PMID 30298062, 2018). "The results showed that IL-1β and IL-12 expression levels were increased in the Ndrg2−/− group together with a decrease in Arg-1 expression levels, revealing a tumor-suppressor phenotype." (PMID 29445150, 2018). "In agreement, IL-1β was demonstrated to play an essential role in the induction of adaptive anti-tumor immune responses." (PMID 29983861, 2018). "On the other hand, MSCs promoted cancer in progressive stages due to the elevation of proinflammatory cytokines (IFNγ, TNFα, IL6 and IL1β) expression in the tumor microenvironment." (PMID 30346985, 2018). "TAMs influence the tumor microenvironment by secreting matrix metalloproteinases (MMPs) or IL-1β and induce vascularization of tumor tissue by producing VEGF, PDGF, and transforming growth factor (TGF)-β." (PMID 28660349, 2018). "This included exosomal MET‐mediated stimulation of proinflammatory cytokine secretion IL‐1β, which subsequently promoted tumour growth and progression in vitro and in vivo." (PMID 30160350, 2018).